IL4 (interleukin 4)
Diseases named in the same sentence as IL4 in open-access papers (continued):
Sharing a sentence is not in itself a finding about the gene and the disease.
periodontitis (continued). "The polymorphisms for IL-4 and IL-13 of Th2 cytokine family are not found to be associated with the pathogenesis of periodontitis." (PMID 35046930, 2021). "Importantly, in addition to the histopathological findings, we observed in the current study that ligature-induced periodontitis showed the increased concentrations of the cytokines IL-17, IL-6, and IL-4 in the heart of mice with gingival inflammation." (PMID 32327711, 2020). "Serum IL-6 levels were elevated, while those of IL-4/18 decreased in patients with periodontitis." (PMID 32698486, 2020). "In addition, the polymorphisms in NLRP3, IL1R, TNF, IL6, IL2, IL4 and IL4RA genes were associated with periodontitis in the males." (PMID 31978095, 2020). "Additionally, in periodontitis granulation tissue Th2 lymphocytes secrete cytokines eliciting humoral type immunity—i.e., IL-4 and IL-10." (PMID 31443525, 2019). "In contrast, in the present series, we observed that other ratios, such as IL1beta/IFNgamma, ILbeta/IL2, ILbeta/IL3 and ILbeta/IL4, may play an essential role in quantitative terms in chronic periodontitis." (PMID 30573746, 2018). "Thus, low level of IL-4 results in higher periodontal destruction and higher levels act as protective role in periodontitis." (PMID 30281626, 2018). "Moreover, IL-4 levels were higher at RSV-treated group on the periodontitis-induced gingival tissue when compared to the non-periodontitis-induced tissue, confirming the protective effect of this marker." (PMID 30281626, 2018). "Finally, a group of genes with multiple functions in humoral immune responses are presented with 8/17 being altered, and only IL4 being consistently decreased in adult and aged periodontitis tissues." (PMID 27486459, 2016). "Allele and genotype frequencies of IL-4 polymorphisms were not significantly different between the subjects with periodontitis and controls (P > 0.05; data not shown)." (PMID 25530681, 2014). "We hypothesized that there would be differences in the percentage of CD4+ T-cells producing IL-4 between patients suffering from aggressive periodontitis compared to patients with chronic periodontitis and healthy controls." (PMID 25299619, 2014). "On the contrary, the initiation and progression of periodontal inflammation may be due to a lack or inappropriate response of the anti-inflammatory cytokines IL-4 and IL-10 in chronic periodontitis." (PMID 23046796, 2012). "Despite so, case-control studies have not shown any relationship between the IL-4 gene polymorphism and susceptibility to chronic periodontitis." (PMID 23046796, 2012). "In addition, the prevalence of Il-1 and Il-4 gene polymorphisms was higher in periodontitis patients with CKD than in those without CKD." (PMID 39652270, 2025). "Moreover, IL-4 and IL-6 are important cytokines in systemic inflammation, and studies have demonstrated that high levels of these cytokines are present in patients with periodontitis." (PMID 35225864, 2022). "Besides, IL-4 is the only cytokine under-expressed in periodontitis individuals but elevated after periodontal treatment, indicating that IL-4 and Th2 cells may have positive effects on periodontal diseases." (PMID 35222410, 2022). "Taken together, these results suggest that the members IL-4 and IL-13 of Th2 cytokine family may not be associated with the pathogenesis of periodontitis." (PMID 35046930, 2021). "The present findings showed that the members IL-4 and IL-13 of Th2 cytokine family may not be associated with the pathogenesis of periodontitis." (PMID 35046930, 2021). "Finally, four of the interleukins reviewed are analyzed separately in four different articles and the results the authors found for each one were as followed: IL-4 was found to be highest in the control group and lowest in the periodontitis group, with intermediate levels for gingivitis." (PMID 24790719, 2014).
periodontitis (continued). "However, in IL-4 levels, a significant decrease was only observed in healthy and gingivitis (p = 0.04 and p = 0.03, respectively), while in IL-12p70 the decrease was significant in all periodontal disease stages (p < 0.0001 for heathy, p = 0.002 for gingivitis, and p = 0.002 for periodontitis)." (PMID 41280935, 2025). "This led to the following research question: What is the effect of closed-field scaling and root planning on serum levels of IL-1β, IL-4, IL-6, IL-8, IL-10, IL-12p70, IL-17A, VEGF, and TNF-α in patients with periodontitis and high blood pressure?" (PMID 40002786, 2025). "Plasma levels of TNF-α and PGE2 were found to be elevated in women with periodontitis compared to periodontally healthy women, while pregnant women with periodontitis showed elevated plasma levels of TNF-α, IL-4, and IL-6." (PMID 38672972, 2024). "IL-4 levels in GCF (pg/site) were 346.30 (77.81) pg, 144.90 (87.84) pg and 15.80 (25.19) pg for the healthy, Stage I-II and Stage III-IV periodontitis groups, respectively." (PMID 37246231, 2023). "The aim of the present study was to investigate any shifts in personalized antimicrobial peptide (LL-37) and cytokine (IL-4, IL-6 and IL-10) profiles in GCF in periodontitis patients subsequent to SRP." (PMID 37246231, 2023). "To confirm the inflammatory conditions within periodontitis gingiva, we observed up-regulation of SDF-1, CCL5, IL-1α, IL-4, and other inflammatory cytokine genes by qPCR." (PMID 36991451, 2023). "There were also detectable levels of other inflammatory mediators such as TGF-β1, IL-1β, IL-2, IL-4, IL-10, IL-12p70, and IL-17A in the GCF samples of periodontitis patients." (PMID 34502071, 2021). "In the chronic phase of periodontitis, CD4+ T lymphocytes differentiate towards an anti-inflammatory Th2 profile, characterized by the production of IL-4, IL-5, IL-6, and IL-10." (PMID 34707462, 2021). "The most important finding was that anti-inflammatory cytokines IL-2, IL-4, and IL-11 levels in GCF of aggressive periodontitis cases were lower compared to chronic periodontitis subjects." (PMID 34104811, 2021). "Regarding intestinal tissue analyses, higher levels of IL-1β, IL-4, IL-6, IL-17A, IL17F, IL-21, IL-31, IL-33 and soluble CD40 ligand (sCD40L) were found in patients having IBD activity and periodontitis." (PMID 34501547, 2021). "Anti‐inflammatory cytokines IL‐4 and IL‐10 have been shown to be lower, or the same, in GCF in RA patients and periodontitis patients than in periodontally healthy controls." (PMID 33954982, 2021). "Regarding intestinal tissue analyses, higher levels of IL-1β, IL-4, IL-6, IL-17A, IL17F, IL-21, IL-31, IL-33 and sCD40L were found in patients with IBD and periodontitis." (PMID 34501547, 2021). "This study evaluated the expression of pro-inflammatory (IL-1β, IL-6, IFN-γ and TNF-α) and anti-inflammatory (IL-4 and TGF-β) cytokines in apical periodontitis lesions." (PMID 29898177, 2018). "During the process of periodontitis, type II helper T lymphocytes (TH2) secrete IL-4, IL-13 and other cytokines that are conducive to B cell humoral immunity and improve the symptoms of inflammation." (PMID 29415708, 2018). "However, IL-17, IL-6, and IL-4 in stage III Grade A and stage IV Grade B periodontitis remained elevated." (PMID 40002786, 2025). "Conversely, IFN-γ, IL-4, IL-6, IL-10, and IL-12p70 exhibited no statistically significant changes across healthy, gingivitis, and periodontitis sites." (PMID 41303313, 2025). "On the other hand, anti-inflammatory cytokines IL-4 and IL-10 showed a negative correlation with periodontitis." (PMID 37246231, 2023). "At the site of periodontitis, the levels of proinflammatory cytokines such as TNF-α, IFN-γ, IL-1, IL-6, IL-12 and G-CSF are significantly increased while anti-inflammatory cytokines are decreased (IL-4 and IL-10)." (PMID 34868054, 2021).
periodontitis (continued). "A third one has shown that the total amount of IL-4 was significantly lower in shallow sites from IBD patients with periodontitis compared to non-IBD patients with periodontitis." (PMID 34501547, 2021). "In patients with periodontitis, lower levels of pro-inflammatory factors IFN-γ, IL-1β, IL-2, IL-6, IL-7, IL-21, TNF-αand higher levels of anti-inflammatory factors IL-4 and IL-5 in gingival crevicular fluid in the Sp group were identified than those in the Dp group." (PMID 33417619, 2021). "IL-4 levels in the serum of patients were higher in chronic periodontitis but these levels did not correlate with the degree of bone loss or pocket formation." (PMID 23046796, 2012). "Moreover, a bi-directional relationship is suggested by several authors because of the increased production of pro-inflammatory cytokines such as IL1B, IL4, IL6, IL10, CBL, and RELA, which are often present in the periodontitis development and CRC carcinogenesis." (PMID 39517401, 2024). "In the present study, the influence of IL-1, IL-4, GATA-3 and COX-2 polymorphisms on the outcomes of non-surgical therapy with and without antibiotics and 2 years of maintenance was analyzed in Caucasian periodontitis patients." (PMID 35806269, 2022). "Besides, the existence of elevated cytokines expression comprising pro‐inflammatory and regulatory cytokines such as IL‐1β, interferon (IFN)‐γ, IL‐1 receptor antagonist (RA), IL‐4, IL‐6, IL‐10, IL‐12, TNF‐α, and induced protein (IP)‐10, lead the way to periodontitis’ inflammatory process." (PMID 34272761, 2021). "As found in the present study, in T2DM patients with periodontitis, statins treatment reduced pro-inflammatory factors IFN-γ, IL-1β, IL-2, IL-6, IL-7, IL-21 and TNF-α levels in GCF, and enhanced anti-inflammatory factors IL-4 and IL-5 levels through the anti-inflammation and anti-oxidation effects." (PMID 33417619, 2021). "In conclusion, periodontitis in the asthmatic mice reduced the inflammatory migrated cells in the BAL (eosinophils, lymphocytes, macrophages), as well as in reduce the levels of the IL-4 and TNF-α cytokines, which was additionally accompanied by a decreased mucus production." (PMID 29145431, 2017). "Thus, the significantly lower GCF levels of IL-4 in deep sites of IBD patients with periodontitis when compared with non-IBD patients with periodontitis may be associated with important immunological alterations when both diseases coexist." (PMID 34501547, 2021). "By contrast to saliva, the inflammatory markers of periodontitis patients showed no marked differences in blood plasma, except for TNF-alpha and partly IL-4." (PMID 41969371, 2026). "Unlike antimicrobial peptide LL-37 and IL-6, IL-4 and IL-10 levels in GCF were substantially lower in the periodontitis groups as compared to healthy individuals at baseline." (PMID 37246231, 2023). "The aim of the present exploratory subanalysis was to evaluate the role of the IL-1A −889, IL-1B +3954, IL-4 −34, IL-4 −590, GATA-3 IVS4 +1468 and COX-2 −1195 gene loci in patients with periodontitis after a non-surgical periodontal therapy with or without additional adjunctive systemic antibiotics." (PMID 35806269, 2022).
influenza (101 papers, 2009 to 2025). An acute viral infection of the respiratory tract, occurring in isolated cases, in epidemics, or in pandemics; it is caused by serologically different strains of viruses (influenzaviruses) designated A, B, and C, has a 3-day incubation period, and usually lasts for 3 to 10 days. "IL-4 and IL-5 have been associated with positive outcomes to infection by Hepatitis B virus and influenza and aid in the clinical recovery of experimental autoimmune encephalomyelitis (EAE) models of multiple sclerosis." (PMID 35805128, 2022). "As expected, genes associated with anti-viral Th1 responses were upregulated following influenza infection (Ifng, Tbet) and genes associated with Th2 responses were downregulated (Il4)." (PMID 33373420, 2020). "AAM and the secretion of IL‐4 and IL‐13 have also been implicated in the increased susceptibility of mice to a secondary pneumococcal infection during recovery of influenza infection." (PMID 29119707, 2018). "The enhanced systemic and mucosal antibody responses were associated with enhanced influenza-specific IL-4 secreting T cell responses." (PMID 23284901, 2012). "In the present study, DE exposure either alone, or during influenza infection significantly increased the expression of IL-4 in association with a later decrease in IFN-γ and IL-12p40 expression." (PMID 21092162, 2010). "The results suggest that elevated levels of IL-4, IL-6, and IL-10, which are associated with Th2 cell activation, might be related to severe influenza, but the increased TNFα and IFNγ levels also need to be paid attention." (PMID 40558593, 2025). "Our findings, showing a decline in IL-4 production with age, suggest that older adults may be at higher risk of poorer influenza outcomes due to reduced T cell-mediated immune responses." (PMID 39456722, 2024). "Moreover, mice that lack functional IL-4 genes clear sub-lethal doses of influenza more efficiently while IL-12 or IFN-γ deficient mice do not." (PMID 21092162, 2010). "DE exposure has been reported to induce the production of Th2 cytokines and since IL-4 decreases clearance of influenza, we hypothesized that the DE enhanced influenza infection was caused by an increase in IL-4." (PMID 21092162, 2010). "In severe influenza cases, the observed Th2-polarized cytokine profile (marked by elevated IL-4, IL-6, and IL-10 levels) is consistent with established pregnancy-associated immune modulation." (PMID 40558593, 2025). "Meanwhile, we also observed that the number of IFN-γ- and IL-4-secreting cells induced by HMP-NPs were ~2.5 times higher than inactivated influenza vaccine." (PMID 39958330, 2025). "The group of pregnant women with severe influenza (PSI) exhibited significantly increased levels of IL-4 and IL-6 compared to the PH3 group and an elevated IL-10 level compared to the CN group." (PMID 40558593, 2025). "We evaluated serum concentrations of seven cytokines (IL-2, IL-4, IL-6, IL-10, TNFα, IFNγ, and IL-17a) as potential biomarkers for influenza severity in pregnant women." (PMID 40558593, 2025). "Previous studies have suggested that IL‐4 shown a protective role in acute lung injury, acute kidney injury and influenza/S." (PMID 40416960, 2025). "Unexpectedly, NKT cells also generate an early wave of IL-4 shortly after influenza infection, reaching its peak on the third day post-infection and accounting for a substantial 70% of IL-4-producing cells in the lymph node." (PMID 38426103, 2024). "The CD1d knockout mice have diminished B cell responses and reduced numbers of IL-4-secreting cells during influenza and vaccinia virus infection." (PMID 39075541, 2024). "Some of the cytokines were very low in the PBS group, especially the signatures for T-cell responses such as IL-4, IL-5, and IL-13, which is in line with the typical type 1 skewed host immune response to influenza infection." (PMID 38711520, 2024).
influenza (continued). "IL-4 expression, however, was the only differentially expressed cytokine between a single and three repeat administrations of influenza vaccine, implying its potential key role in mediating the anti-tumor response." (PMID 38203396, 2023). "Here, we protected mice from lethal influenza infection by administering IL-4 in complex with anti-IL-4 Ab." (PMID 38037190, 2023). "In contrast, splenocytes isolated from mice vaccinated against influenza vaccination that were exposed to acidic oligosaccharide ex vivo had lower secretion of Th2 cytokines (IL-4, IL-5, and IL-10)." (PMID 38179055, 2023). "Studies conducted on mice showed that exercising significantly increased IL-4 lung protein levels which is involved in initiating the production of antibodies against viruses leading to reduced lung inflammation during influenza infection." (PMID 36137134, 2022). "For example, it reported that IL-28B is an important regulator of the Th1/Th2 balance by increasing Th1-type cytokines (IFN-γ) and decreasing Th2-type cytokines (IL-4, IL-5 and IL-13) during influenza vaccination." (PMID 34818327, 2021). "In mouse studies, IL-4 and IL-13 production was also observed after vaccination with an inactivated influenza/AS03 formulation." (PMID 34315825, 2021). "There was a higher number of lung infiltrating CD4+ T cells after influenza infection of Siglec-H ko mice compared to wt mice and among these a higher IL-4 production." (PMID 34497606, 2021). "Total CD4 T cell reactivity at any time point was defined as the total number of cells that produce any of the 4 effector responses (IFNγ, Granzyme B, IL-4 and IL-10) to the different MPs from all 4 influenza strains." (PMID 33922875, 2021). "In mouse studies, IL-4 and IL-13 production was also observed following vaccination with an inactivated influenza/AS03 formuation." (PMID 33688652, 2021). "Herein, we report that the combination of agonistic anti-CD40, IL-4 and IL-21 affords polyclonal B cell stimulation that was comparable to R848 and IL-2 for detection of influenza-specific memory B cells." (PMID 32069813, 2020). "Culturing B cells in the presence of anti-CD40, IL-4 and IL-21 was found to trigger influenza antigen-specific ASC in frequencies similar to R848 and IL-2 stimulation." (PMID 32069813, 2020). "To this end, we analyzed IL-4 production by both CXCR3− and CXCR3+ NKT cell groups on day 3 of influenza infection by flow cytometry and enzyme-linked immunospot (ELISPOT)." (PMID 29249358, 2018). "To gain insight into the kinetics of IL-4 production by NKT and TfH cells after influenza infection, we took advantage of IL-4 GFP reporter mice, which concomitantly express endogenous levels of IL-4 in addition to GFP." (PMID 29249358, 2018). "We found an increase in the levels of the inflammatory cytokines IL-1α, IL-1β, TNFα, IL-6, IL-12p40, IL-17, and IFNγ, and increased levels of the Type 2 cytokines IL-4 and IL-5, in influenza-infected Stat2−/− mice when compared to WT mice." (PMID 30337919, 2018). "So far, we have defined the temporal frame of IL-4 production by NKT cells during the early stages of influenza infection." (PMID 29249358, 2018). "Altogether, our results indicate that the early wave of IL-4 triggered after influenza infection is critical for the induction of B cell responses." (PMID 29249358, 2018). "Levels of the cytokines IFN-γ and IL-4, associated with Th1-type and Th2-type immune responses, respectively, were determined to evaluate the influence of fliC adjuvant on H7N9 influenza subunit vaccine in SPF chickens." (PMID 28637471, 2017). "To assess the impact of the topically applied EGFRI on cytokine production and immune cell activation, we measured levels of IFN-γ and IL-4 producing influenza-specific lymphocytes in the skin-draining lymph nodes and spleens of vaccinated mice." (PMID 26227481, 2015).